OASL (2'-5'-oligoadenylate synthetase like)
Diseases named in the same sentence as OASL in open-access papers (continued):
Sharing a sentence is not in itself a finding about the gene and the disease.
breast carcinoma (11 papers, 2020 to 2025). "The mutational spectrum of OAS1, OAS2, OAS3, and OASL genes in breast cancer patients from the TCGA dataset was investigated using the cBioportal database." (PMID 39633486, 2024). "High mRNA expression of OAS1 (HR = 2.01, 95%CI: 1.26–3.18, p = 0.0026), OAS3 (HR = 1.72, 95%CI: 1.13–2.64, p = 0.011) and OASL (HR = 1.8, 95%CI: 1.17–2.77, p = 0.0066) was significantly associated with worse OS in grade 2 breast cancer." (PMID 32560641, 2020). "The OAS family genes (OAS1, OAS2, OAS3, and OASL) were found to be significantly upregulated in breast cancer cell lines and tissues compared to normal controls." (PMID 39633486, 2024). "A total of five drugs, Acetaminophen, Estradiol, Cyclosporine, Calcitriol, and Seocalcitol, demonstrated the capability to potentially reduce the expression levels of OAS1, OAS2, OAS3, and OASL, suggesting their prospective use in breast cancer treatment." (PMID 39633486, 2024). "Overall, these results highlight the critical roles of OAS1, OAS2, OAS3, and OASL in supporting the growth and proliferation of breast cancer cells, while also suggesting their involvement in modulating cellular migration." (PMID 39633486, 2024). "To investigate the correlation between the expression levels of OAS1, OAS2, OAS3, and OASL genes and the survival outcomes in breast cancer patients, we utilized the Kaplan-Meier Plotter online bioinformatics tool." (PMID 39633486, 2024). "Utilizing the TISIDB database, we explored the relationship between OAS1, OAS2, OAS3, and OASL expression in breast cancer across various immune and molecular subtypes." (PMID 39633486, 2024). "The results uncovered a significant correlation between the expression of OAS1, OAS2, OAS3, and OASL and all immune molecule subtypes in breast cancer." (PMID 39633486, 2024). "Results from UALCAN and GEPIA indicated that the mRNA levels of OAS1, OAS2, OAS3, and OASL were markedly higher (p-value < 0.05) in breast cancer samples compared to normal samples, aligning with the outcomes observed in cell lines." (PMID 39633486, 2024). "Next, we validated the promoter methylation levels of OAS1, OAS2, OAS3, and OASL genes in both breast cancer and control samples utilizing the OncoDB database." (PMID 39633486, 2024). "The constructed predictive model showed that OAS1, OAS2, OAS3, and OASL genes can effectively predict the overall survival of breast cancer patients." (PMID 39633486, 2024). "Our study observed significant correlations between the expression of OAS1, OAS2, OAS3, and OASL and various molecular and immune subtypes of breast cancer." (PMID 39633486, 2024). "The experimental data revealed significantly elevated mRNA levels of OAS1, OAS2, OAS3, and OASL in breast cancer cell lines relative to normal controls (p-value < 0.05)." (PMID 39633486, 2024). "The relationship between OASL and cancer has been reported, such as breast cancer, cervical cancer, kidney cancer, and lung cancer." (PMID 36162993, 2022). "Previous studies have shown that high mRNA expression of OASL and OAS3 was associated with poor prognosis in all breast cancer patients." (PMID 34616451, 2021). "Other studies have revealed that OASL was regulated by upstream long noncoding RNA TINCR to promote the metastasis of breast cancer." (PMID 34616451, 2021). "High mRNA expression of OAS2 (HR = 0.26, 95%CI: 0.1–0.67, p = 0.0027), OAS3 (HR = 0.43, 95%CI: 0.26–0.7, p < 0.001), and OASL (HR = 0.47, 95%CI: 0.27–0.83, p = 0.0078) was correlated with better OS in basal-like breast cancer." (PMID 32560641, 2020). "For example, OASL was overexpressed in breast cancer and esophageal cancer, but reduced in colon cancer and lung cancer." (PMID 33229623, 2020). "In HER2-overexpressing breast cancer patients, high mRNA expression of OASL was correlated with favorable OS (HR = 0.49, 95%CI: 0.25–0.96, p = 0.035)." (PMID 32560641, 2020).
breast carcinoma (continued). "High mRNA expression of OAS3 (HR = 0.65, 95%CI: 0.47–0.9, p = 0.0088) and OASL (HR = 0.62, 95%CI: 0.44–0.86, p = 0.0035) was found to be correlated with better OS in grade 3 breast cancer." (PMID 32560641, 2020). "The findings indicated that OAS1, OAS3, and OASL genes did not exhibit mutations among the 986 analyzed breast cancer samples." (PMID 39633486, 2024). "Furthermore, the findings from GEPIA revealed that the expressions of OAS1, OAS2, OAS3, and OASL genes were notably more pronounced in the advanced stages of breast cancer compared to the early stages." (PMID 39633486, 2024). "Furthermore, OASL (potential prognostic biomarker in breast cancer) was only found in one of our 10 K EVs, suggesting that the cargo of 10 EVs contains oncogenic material." (PMID 37190292, 2023). "The results revealed that breast cancer patients exhibiting increased expression of OAS1, OAS2, OAS3, and OASL genes had poor overall survival." (PMID 39633486, 2024). "To further investigate the functional roles of the OAS family genes in breast cancer, we designed four siRNAs targeting OAS1, OAS2, OAS3, and OASL and transfected them into HOC1 cells." (PMID 39633486, 2024). "In breast cancer, for instance, there is a notable upregulation of OAS genes such as OAS1, OAS2, OAS3, and OASL." (PMID 39633486, 2024). "The knockdown of OAS1, OAS2, OAS3, and OASL in HOC1 cells, validated by qRT-PCR and Western blot analyses, revealed their critical roles in breast cancer." (PMID 39633486, 2024). "We studied the effect of resveratrol, genistein, apigenin and thymoquinone at non- toxic concentrations on the expression activation of type I IFN signaling genes (IFN-responsive genes IFI27 and OASL, and IFN regulatory factor IRF1) in another cell line, T47D (human breast cancer cells)." (PMID 39796235, 2025). "Notably, our findings indicate that the genes upregulated by O-desmethyltramadol in both breast cancer cell lines—IFIT1, GBP4, SECTM1, and OASL—are regulated by interferon." (PMID 40362379, 2025). "The comprehensive examination of the mutational landscape of OAS1, OAS2, OAS3, and OASL genes in breast cancer patients revealed that OAS1, OAS3, and OASL exhibited an absence of mutations in all 986 analyzed breast cancer samples." (PMID 39633486, 2024). "Given that OAS1–3 and OASL both belong to the OAS family, it is noteworthy to systematically explore whether OAS family members could be prognostic indicators in breast cancer." (PMID 32560641, 2020). "High mRNA expression of OAS2 (HR = 0.34, 95%CI: 0.17–0.67, p = 0.0011) was correlated with better OS in luminal A type cancers, whereas OASL was not related to prognosis in luminal A breast cancer." (PMID 32560641, 2020). "Furthermore, our findings indicate a noteworthy negative correlation between OAS1, OAS2, OAS3, and OASL elevated gene expression and a substantial decrease in promoter methylation levels across breast cancer tissues." (PMID 39633486, 2024). "Additionally, results from HPA demonstrated a significant elevation in protein expression levels of OAS1, OAS2, OAS3, and OASL in breast cancer tissue samples as opposed to normal tissue samples." (PMID 39633486, 2024).
influenza (10 papers, 2011 to 2024). An acute viral infection of the respiratory tract, occurring in isolated cases, in epidemics, or in pandemics; it is caused by serologically different strains of viruses (influenzaviruses) designated A, B, and C, has a 3-day incubation period, and usually lasts for 3 to 10 days. "Specifically, influenza samples maintained higher levels of type I IFN response–associated antiviral ISGs (e.g., IFITM1, IFITM2, IFITM3, OAS2, OAS3, OASL) and antigen presentation genes (e.g., HLA-DRB5, HLA-C, B2M, HLA-B, HLA-E)." (PMID 34618691, 2021). "Thirdly, although it is accepted that the current study provides useful baseline data for future study, an ideal approach should be to perform a prospective study to verify the usefulness of OASL as an influenza ARI biomarker." (PMID 32714913, 2020). "Interferon-inducible 2′-5′-oligoadenylate synthase (OAS) and OAS-like protein (OASL) are two related ISGs in humans, which are known to restrict influenza." (PMID 32477965, 2020). "MX1, OASL and IFIT5 genes encode proteins with known functions in influenza defense." (PMID 32381003, 2020). "When OASL was knocked out of DF-1 cells, the cells became more permissive to influenza infection." (PMID 32477965, 2020). "Thereafter, we suggested that a combination of both OASL and universal influenza detection, as measured by qRT-PCR using nasal samples, could be utilized to identify influenza infection in individuals with flu-like illness." (PMID 32714913, 2020). "Moreover, OASL was revealed as a biomarker that could identify influenza patients from among those with flu-like ARI." (PMID 32714913, 2020). "However, OASL was found to be upregulated during the progression of influenza infection." (PMID 32714913, 2020). "Firstly, both OASL and IFI27 shared similar highly accurate performance in discriminating between influenza and bacterial infections on GSE6269." (PMID 32714913, 2020). "Similarly, hsa-miR-5003-3p, EP300, Valproic Acid, Influenza, and ELAVL1 have interactive relationships centered around EIF2AK2, while hsa-miR-6893-3p, EP300, Calcitriol, Influenza, and HNRNPA2B1 exhibit interactive relationships centered around OASL." (PMID 38601162, 2024). "OASL expression profiling triggered by various infections was different enough to discriminate between influenza and non-influenza ARI infections." (PMID 32714913, 2020). "As the OASL expression value was important and influenza is an RNA virus, we suggested using qRT-PCR to detect both OASL expression and influenza virus to distinguish between influenza and non-influenza flu-like cases in clinical settings." (PMID 32714913, 2020). "The exact mechanism of OASL induction by de novo KSHV infection or reactivation is not known, but OASL is induced by Sendai and influenza infection in an IRF3-dependent manner." (PMID 29499066, 2018). "However, OASL's expression value measured by qRT-PCR can be sufficient to differentiate influenza from other non-influenza viral infections." (PMID 35186993, 2022). "Therefore, identification of OASL expression might indicate the presence of an influenza infection when PCR indicated a negative result." (PMID 32714913, 2020).
lung carcinoma (8 papers, 2017 to 2022). "The OASL gene has been found to be associated with the regulation of lung cancer cell sensitivity to acRoots, via the PI3K signal pathway." (PMID 34439992, 2021). "Previous research indicated that OASL may be crucial for maintaining lung cancer cell susceptibility to Actinidia chinensis Planch root extract and might be associated with the development of drug resistance." (PMID 33229623, 2020). "The RPS2 and OASL were considered to be a potential therapeutic target in prostate cancer and lung cancer." (PMID 33133154, 2020). "A previous study showed that OASL gene upregulation is involved in the inhibition of lung cancer cell proliferation and apoptosis." (PMID 31949544, 2019). "So far, there have been studies on the important role of OASL gene in the treatment of lung cancer." (PMID 36162993, 2022). "OASL may play a crucial role in adjusting the sensitivity of lung cancer cell and development of drug resistance to acRoots." (PMID 32508044, 2020). "Besides, OASL is closely related to the occurrence of lung cancer." (PMID 36162993, 2022). "Preclinical evidence showed that acRoots could inhibit the growth of lung cancer cell and increase its apoptosis by altering immune‐associated gene profiles via the phosphatidylinositol 3‐kinase (PI3K)‐2′‐5′‐oligoadenylate synthetase like (OASL) signal pathway." (PMID 32508044, 2020). "Our microarray data analysis revealed and RT-qPCR confirmed the increased mRNA expression of all of the OAS gene family members (OAS1, OAS2, OAS3, OASL) and XAF1 and IRF7 in the lung cancer cell line A549 after transfection with BNC2." (PMID 28184177, 2017).
gastric cancer (6 papers, 2019 to 2025). A primary or metastatic malignant neoplasm involving the stomach. "This study investigates the role of 2’-5’ oligoadenylate synthetase-like (OASL) in Oxaliplatin (OXA)-induced immunogenic cell death (ICD) in Gastric cancer (GC) cells through the cGAS-STING signaling pathway." (PMID 41271618, 2025). "OAS1, OAS2, OAS3, and OASL have been recognised as pivotal genes in a bioinformatic study focusing on trastuzumab-resistant gastric cancer." (PMID 36567857, 2022). "Our previous research indicated that OAS1, OAS2, OAS3 and OASL were all identified as hub genes from the protein-protein interaction network of differentially expressed genes between the trastuzumab-resistant gastric cancer and control groups." (PMID 32560641, 2020). "For HER2+ gastric cancer, the high expression of VIM, IFI44, IFI44L, IFIT2, IFIT3, ISG15, OAS1, or OASL was associated with worse overall survival (P < 0.05)." (PMID 31949544, 2019). "In trastuzumab-resistant gastric cancer, OAS1, OAS2, OAS3, and OASL were all identified as key genes." (PMID 38380081, 2024). "While established mechanisms of OXA resistance in gastric cancer involve JUNB-mediated MAPK hyperactivation, EphA2-induced EMT, METTL3-dependent DNA repair/stemness maintenance, and LINC00641-regulated autophagy, our study reveals a distinct immunosuppressive axis mediated by OASL." (PMID 41271618, 2025).
autoimmune disease (5 papers, 2015 to 2024). A disorder resulting from loss of function or tissue destruction of an organ or multiple organs, arising from humoral or cellular immune responses of the individual to their own tissue constituents. "The main role of OAS family is regarded as an immunomodulator, and OASL level is associated with autoimmune diseases and chronic infections." (PMID 38434138, 2024). "It has recently been found that OASL may act as a biomarker or predictor of therapeutic responses in autoimmune disease." (PMID 35183246, 2022). "The expression pattern of OASL may offer useful information for treating autoimmune diseases and chronic infections." (PMID 32669126, 2020). "Recent studies have found that OASL may participate in the pathogenesis of the autoimmune disease." (PMID 35183246, 2022).
pancreatic cancer (5 papers, 2021 to 2025). "Results derived from these three databases all indicated that elevated levels of OAS1, OAS2, OAS3, and OASL were associated with poor overall survival (OS) in pancreatic cancer." (PMID 35719943, 2022). "OASL, as the most significant positive correlation with the expression of OAS1, was conformed that the high expression of OASL was also associated with poor OS in pancreatic cancer." (PMID 35898870, 2022). "Among 21 genes from the immune-related signature, MET, OAS1, and OASL were significantly associated with prognosis of pancreatic cancer patients." (PMID 33869254, 2021). "Among them, MET, OAS1, and OASL were verified to be markedly up-regulated in pancreatic cancer and associated with poor clinical outcomes of patients." (PMID 33869254, 2021). "MET, OAS1, and OASL mRNAs were all up-regulated in pancreatic cancer and associated with unfavorable prognosis." (PMID 33869254, 2021). "Among these genes, MET, OAS1, and OASL were validated to be up-regulated in pancreatic cancer and associated with unfavorable prognosis of patients." (PMID 33869254, 2021). "The expression level of OASL in pancreatic tumor samples with different clinical grades and stages was higher than normal pancreatic samples." (PMID 39990208, 2025). "Simultaneously, the protein expression level of OASL was significantly higher in pancreatic tumor samples than normal samples according to the CPTAC database." (PMID 39990208, 2025). "We validated the impact of OASL on apoptosis, migration, and invasion in pancreatic cancer cell lines." (PMID 39286258, 2024). "Western blotting results showed that the protein expression levels of OAS1, OAS2, OAS3, and OASL were significantly elevated in pancreatic cancer cells compared with normal pancreatic cells." (PMID 35719943, 2022). "The potential prognosis values of OAS1, OAS2, OAS3, and OASL in pancreatic cancer were investigated using Kaplan-Meier Plotter, GEPIA, and OncoLnc databases." (PMID 35719943, 2022). "Immunohistochemical stains of OAS1, OAS2, OAS3 and OASL proteins in human pancreatic cancer tissues and normal pancreatic tissues were searched from the HPA database." (PMID 35719943, 2022). "We further analyzed the mRNA levels of OAS1, OAS2, OAS3, and OASL in pancreatic cancer tissues and normal pancreatic tissues based on Oncomine and GEPIA databases." (PMID 35719943, 2022). "The co-expressed genes that related to OAS1, OAS2, OAS3, and OASL were respectively identified in Pei Pancreas dataset of Oncomine database with 16 normal pancreatic tissues and 36 pancreatic carcinoma tissues." (PMID 35719943, 2022). "In Pei Pancreas dataset, OAS3 was 6.317 times higher in pancreatic carcinoma compared to normal tissues, In Logsdon Pancreas dataset, OASL was 77.098 times higher in pancreatic adenocarcinoma compared to the normal pancreatic tissues." (PMID 35719943, 2022). "The expression of MET, OAS1, and OASL in pancreatic cancer was verified in the GSE15471 and GSE62452 datasets." (PMID 33869254, 2021). "We identified three key genes (MET, OAS1, and OASL) that were all up-regulated in pancreatic cancer and indicated an unfavorable prognosis." (PMID 33869254, 2021). "In addition, by analyzing the GEPIA database, the mRNA levels of OAS1, OAS2, OAS3, and OASL were all significantly higher in pancreatic cancer tissues than normal pancreatic tissues." (PMID 35719943, 2022). "Collectively, we identified three immune-related prognostic genes MET, OAS1, and OASL, which could be promising therapeutic targets as well as prognostic markers for pancreatic cancer." (PMID 33869254, 2021). "The immunohistochemical staining of OASL and MHC-I was performed in normal pancreas and pancreatic cancer tissues of humans." (PMID 39990208, 2025). "Thus, MET, OAS1, and OASL could be potential therapeutic markers in pancreatic cancer." (PMID 33869254, 2021).
systemic lupus erythematosus (5 papers, 2015 to 2024). An autoimmune multi-organ disease typically associated with vasculopathy and autoantibody production. "OASL variants (such as R60W, T261S, A447V) significantly accumulate in patients with systemic lupus erythematosus (SLE), promoting the secretion of IFN-α." (PMID 39286258, 2024). "One example is systemic lupus erythematosus, a disorder associated with skin and joint inflammation, accelerated atherosclerosis, and upregulation of genes such as IFI6 and OASL." (PMID 31539532, 2020).